TNF (tumor necrosis factor)
Diseases named in the same sentence as TNF in open-access papers (continued):
Sharing a sentence is not in itself a finding about the gene and the disease.
COVID-19 (continued). "Further indirect support comes from observational studies of patients with autoimmune inflammatory diseases, where chronic TNF-α inhibitor therapy significantly reduced the odds of hospitalisation and severe COVID-19 outcomes (defined as ICU admission or death)." (PMID 40481519, 2025). "During acute COVID-19, CD25 levels were positively associated with several serum inflammation markers, including C-reactive protein (CRP), IL-1β, IL-6, IL-10, and tumor necrosis factor (TNF)." (PMID 41310351, 2025). "An analysis of data from various registry-based and national cohort studies suggests that patients with axSpA, particularly those receiving TNF-α inhibitor monotherapy, do not face an increased risk of hospitalization or mortality due to COVID-19." (PMID 40142222, 2025). "We compared the proteome of children hospitalised with acute COVID-19 with a matched seronegative healthy control cohort, identifying a number of differentially expressed proteins, which were related to TNF pathway activation, and L1 cellular adhesion molecule interactions." (PMID 40826070, 2025). "Indeed, we observed that this HLA-B -21 dimorphism leads to differences in IFN-γ release as well as TNF-α concentrations, suggesting its impact on the cellular response in kidney transplant recipients after COVID-19 vaccination." (PMID 41153412, 2025). "In addition, the cytokine storms observed in severe COVID-19, characterized by elevated levels of interleukin-6 (IL-6) and tumor necrosis factor-alpha (TNF-α), directly stimulate VEGF-A secretion from activated endothelial and immune cells." (PMID 40075026, 2025). "TNF signalling has been suggested as the therapeutic target for COVID-19." (PMID 40300201, 2025). "Smoking is linked to the exacerbation of respiratory infections, including COVID-19; it promotes inflammation by the excess production of TNF-α and transforming growth factor β (TGF-β), and diverse interleukins (IL) such as IL-1β, IL-12, IL-17, and IL-23 also have an impact on gene expression." (PMID 40142222, 2025). "Moreover, cytokine release syndrome characterized by TNF-α, IL-6, and IL-1β was associated with disease severity and, higher levels of IL6 were more predictive for COVID-19 mortality." (PMID 40121473, 2025). "Notably, IL-6 and TNF-α blockade therapies, such as the IL-6 receptor inhibitor tocilizumab, have effectively reduced mortality in severe COVID-19 patients." (PMID 40643149, 2025). "The increase in IL-6, IL-12, and TNF-α levels in HUVEC supernatants further supports our hypothesis regarding the dynamic regulation of inflammatory mediators in response to COVID-19." (PMID 41583455, 2025). "Among these, elevated levels of IL-6, CRP, and tumor necrosis factor alpha (TNFα) for one or more months after SARS-CoV-2 infection were indicators that patients may experience long-COVID-19 symptoms." (PMID 39859366, 2025). "TNF-α and IL-8 were identified as associated with COVID-19 severity, but with no replication support." (PMID 41359762, 2025). "Yet, our data showed lower levels of TNF-α in critical COVID-19 patients at admission." (PMID 40508859, 2025). "One of the key drivers of organ damage in severe COVID-19 is the cytokine storm—an exaggerated systemic inflammatory response characterized by the release of high levels of proinflammatory cytokines such as IL-6, TNF-α, and IL-1β." (PMID 40430148, 2025). "Apoptosis mediated by the FAS-FASL pathway, which is sustained by the continual stimulation of cytokines such as TNF and IL-6, may have been involved in the lymphocyte death seen in the spleens of the COVID-19 patients studied herein." (PMID 41210940, 2025). "The clinical worsening of individuals with COVID-19 may be related to immunopathological damage, reflected by increased concentrations of proinflammatory cytokines such as tumor necrosis factor alpha (TNF-α) and interleukin 6 (IL-6)." (PMID 41394849, 2025).
COVID-19 (continued). "In line with this, several lines of research suggest that post-COVID-19 may involve persistent (neuro) inflammation, indicated by increased levels of pro-inflammatory cytokines such as TNF-α, IL-1β, and IL-17A." (PMID 40686929, 2025). "Cytokine storm including inflammatory cytokines IL-1β, IL-6, IL-17, and TNF-α could be provoked in moderate and severe COVID-19 patients." (PMID 41235116, 2025). "It has been reported that patients with T2DM and COVID-19 have elevated levels of proinflammatory cytokines, such as IL-6 and TNF-α, as well as higher white blood cell counts (such as neutrophils), suggesting a heightened inflammatory response compared to patients without T2DM." (PMID 41009326, 2025). "Furthermore, the long-term persistence of high plasma levels of IL–1β, IL–6, and TNF in patients with COVID-19 symptoms opens up therapeutic options based on blocking the signaling of these cytokines." (PMID 40217938, 2025). "Indeed, COVID-19 triggers a hyperinflammatory response—also known as a cytokine storm—which is marked by elevated levels of pro-inflammatory cytokines such as IL-6, TNF-α, and IL-1β." (PMID 40217761, 2025). "Similarly, regarding inflammatory cytokines, high levels of several cytokines, such as IL-1β, IL-2, IL-6, IL-7, IL-8, IL-10, CXCL10/IP-10, MCP-1, and TNF-α have already been described according to the severity of COVID-19." (PMID 39861879, 2025). "This Th1/IL-2-driven profile is frequently associated with effective immunity: in COVID-19, convalescent patients with favorable outcomes exhibit polyfunctional CD4+ T cells secreting IL-2, IFN-γ, and TNF-α, whereas severe cases often show loss of this functionality." (PMID 41357245, 2025). "In contrast, TNF-α inhibitors are currently undergoing clinical evaluation, with concerns remaining regarding their safety and therapeutic specificity in the context of post-acute COVID-19." (PMID 40507911, 2025). "Consequently, TNF-α inhibitors hold promise as a therapeutic strategy to modulate the inflammatory response and potentially improve clinical outcomes in severe COVID-19 cases." (PMID 40481519, 2025). "Studies have shown that systemic administration of ozone in COVID-19 patients shortened hospitalization time, reduced proinflammatory cytokine levels (IL-2, IL-6, IL-8, TNF-α), and simultaneously increased concentrations of the anti-inflammatory cytokine IL-10." (PMID 41614780, 2025). "Also, increased levels of the endothelial tPA receptor, annexin A2, correlated with inflammatory markers (i.e., IL-1β, IL-6, and TNF-α) and COVID-19 magnitude." (PMID 38378550, 2024). "Additionally, T-cells in COVID-19 patients exhibited three distinct mechanisms of active apoptosis: the X-linked inhibitor of apoptosis (XIAP)-associated factor 1 (XAF1) pathway, the TNF pathway, and the Fas receptor pathway." (PMID 38542251, 2024). "In fact, the pattern of pro-inflammatory cytokines induced in COVID-19 is similar to target cytokines for RA treatment; Several studies have showed that primary epithelial cells are infected with COVID-19, serve as a source of cytokines, and secrete TNF-α., IL-6, IL-1 and IL-8." (PMID 39211019, 2024). "However, anti-TNF therapy has not been associated with increases in SARS-CoV-2 replication or COVID-19 severity, suggesting that TNF has minimal anti-viral activity against SARS-CoV-2 during COVID-19." (PMID 38803494, 2024). "According to univariate logistic regression, the odds of a severe COVID-19 diagnosis were 2.62 and 2.58 times higher in patients with a high IP-10 and TNF-α concentration at T0 compared to patients with a low concentration (p = 0.240 and p = 0.239), respectively." (PMID 39194742, 2024). "COVID-19 patients displayed elevated levels of IL-1β, IL-6, and TNF." (PMID 38392902, 2024). "Thus, the present study aimed to investigate the association between the severe form of acute COVID-19 and long COVID with the gene expression of STING and cGAS and the plasma levels of IFN-α, TNF-α and IL-6." (PMID 38424312, 2024).
COVID-19 (continued). "In COVID-19 patients, the level of tumor necrosis factor-α (TNF-α) was higher compared to controls." (PMID 39188881, 2024). "Notably, the cytokine levels were significantly elevated in the COVID-19 patients compared to the control group P-values were < 0.001, 0.001, 0.008, and 0.008 for TNF-α, IL-6, IL-17, and IFN-γ, respectively." (PMID 38459174, 2024). "Since, IL-6 and Tumor necrosis factor-alpha (TNF-α) levels are the major contributors of cytokine storm syndrome in the lungs during COVID-19, we also evaluated the mRNA expression of IL-6 and Tumor necrosis factor-alpha (TNF-α) in the vaccinated vs. unvaccinated hamsters." (PMID 39911577, 2024). "It is well established that viral infections such as COVID-19 are characterised by increases in pro-inflammatory cytokines such as IL-6, TNF-α, IL-12p40, and IL-23, while influenza and HIV-1 infections are characterised by increased production of IL-1β, IL-6, and TNF-α." (PMID 39123583, 2024). "In the case of COVID-19, an impaired type I interferon response associated with a persistent blood virus load and an exacerbated inflammatory response driven by NF-κB, particularly by increased TNF-α and IL-6 production, were observed in a cohort of fifty COVID-19 patients." (PMID 39125989, 2024). "The progression of COVID-19 is often accompanied by an upsurge in proinflammatory endogenous cytokines, including interleukin-1 (IL-1), interleukin-6 (IL-6), and tumor necrosis factor-alpha (TNF-alpha)." (PMID 38511750, 2024). "However, in this study, we determined the molecular structure and receptors of IL-6 and TNFα alongside the function of pro-inflammatory cytokines TNFα and IL-6 involved in the pathogenesis of COVID-19." (PMID 39118801, 2024). "Moreover, the systemic inflammatory response triggered by COVID-19, characterized by elevated levels of pro-inflammatory cytokines (e.g., IL-6, TNF-a), can exacerbate liver injury through immune-mediated mechanisms and microvascular thrombosis." (PMID 39492990, 2024). "We detected significantly higher inflammatory responses in COVID-19 positive pregnant women evident by increased IL-6 and TNF-α, which have been reported to induce the likelihood of preterm birth and can impact the development of the fetal neurological and respiratory system." (PMID 39048938, 2024). "Gene set enrichment analysis (GSEA) revealed that 2°BP was characterized by downregulated TNFα signaling via NF-κB in, suggesting that a state of suppressed antibacterial defense might characterize 2°BP in COVID-19 patients." (PMID 39472555, 2024). "Notably, exposure of ECs to COVID-19 plasma characterized by elevated proinflammatory cytokine levels (specifically, IL-1β, IL-6, and TNF-α) precipitated a redox-sensitive upregulation of SGLT-2 expression." (PMID 38448675, 2024). "Also, this observation is similar to what was found in COVID-19 in which the magnitude of the increase in the serum concentration of TNF predicts the prognosis of the disease." (PMID 39152892, 2024). "Acute respiratory SARS-CoV-2 infection generates a robust systemic cytokine response in addition to type I and type II interferon responses, and the plasma levels of IFN-α, IFN-γ, IL-1β, IL-6, and TNF-α are significantly increased in human patients with acute COVID-19." (PMID 39062017, 2024). "The analyses showed that COVID-19 patients with cardiovascular co-morbidities who also consumed statins had significantly lower plasma levels of IL-6 (adjusted p = 0.027), TNFα (adjusted p = 0.036), and IL-10 (adjusted p = 0.025) compared to COVID-19 patients with no CVD co-morbidities." (PMID 39518552, 2024). "Moreover, the elevation of TNF-a and IL17a in severe COVID-19 cases invites further investigation into their potential as biomarkers for predicting disease progression and as targets for therapeutic intervention." (PMID 39203987, 2024). "On the other hand, studies have shown that IL-6 and TNF-α levels increase in COVID-19 patients." (PMID 38524183, 2024).
COVID-19 (continued). "The effects may be induced by the combined systemic interferon and TNF-α responses at the acute phase and may contribute to post-COVID-19 persistent muscle fatigue." (PMID 39062017, 2024). "Importantly, elucidation of putative serum mediators revealed a significant upregulation of key cytokines in COVID-19 positive patients compared to controls, including IL-6, TNF-α, IL-1β, IL-10, and CRP." (PMID 38041432, 2024). "Targeting TNF-α/IFN-γ in combination with TLR4 may represent a promising therapeutic approach for alleviating CRS in individuals with COVID-19." (PMID 39359733, 2024). "Moreover, attention should be paid to the boosted levels of IFNG and TNF in COVID-19, as synergism of TNF-α and IFNG triggers inflammatory cell death, tissue damage, and mortality in SARS-CoV-2 infection." (PMID 39066192, 2024). "Moreover, IL-10, IL6 and TNF-alpha, also biomarkers of COVID-19 severity, were exclusively upregulated in the placebo group at the protein level in serum." (PMID 38649734, 2024). "The polymorphisms in TNFα -308 G>A (rs1800629), IL-8 -251T>A (rs4073), IL-10 (-1082 G>A), rs1800896 and CXCR2 +785 C>T (rs2230054) are associated with the risk of susceptibility to COVID-19 and with mortality in COVID-19 patients." (PMID 38544825, 2024). "Thus, genetic polymorphisms that affect the expression of genes encoding these cytokines (TNF and IFNG) are natural candidates for prognostic and predictive biomarkers in COVID-19." (PMID 38675991, 2024). "The inhibition of TNF not only decreases the levels of biologically active TNF but also mitigates the production of other pro-inflammatory cytokines that contribute to the hyperinflammatory response observed in COVID-19 patients." (PMID 39459457, 2024). "Another pathological pathway is represented by the dysregulation of the immune system and, because of the activation of endothelial cells and macrophages, a hyperinflammatory phase appears during COVID-19 with the enormous release of TNF-α, IL-1, IL-2, IL-6, IL-8, and chemokines." (PMID 38999316, 2024). "However, Neurath’s research has raised doubts regarding the efficacy of TNF inhibitors in preventing severe outcomes in COVID-19 cases." (PMID 39459457, 2024). "A high expression of IL-6 and TNF-α characterizes the cytokine storm in COVID-19." (PMID 39063142, 2024). "In the hyperinflammatory state, such as critical phase of COVID-19 with the acute elevation of tumor necrosis factor (TNF)-α and interleukin (IL)-6, serum concentrations of HDL-C and apoA-I significantly decreased and were negatively correlated with COVID-19 severity." (PMID 38791598, 2024). "Their study revealed that the consumption of NBS powder over a duration of 4 weeks yielded a significant influence on the levels of proinflammatory cytokines, particularly interleukin-6 (IL-6) and tumor necrosis factor α (TNF-α), in individuals afflicted with COVID-19." (PMID 38522056, 2024). "Therefore, monoclonal antibodies targeting TNF-α are likely to intensify the inflammatory responses seen in COVID-19, reducing the release of other agents that worsen inflammation." (PMID 38392902, 2024). "Indeed, recent evidence suggests that elevated IL-6 and TNF-α levels can predict disease severity and survival in patients with COVID-19." (PMID 39113083, 2024). "Similarly, the same combination of cytokines has been described as an effective approach to induce cell death in cancer cells, and high levels of TNFα and IFNγ are supposed to be responsible for the inflammatory cell death in severe COVID-19 patients." (PMID 38542436, 2024). "Additionally, miR-126 and miR-451a correlate with TNF-α levels after receiving the initial dose of the COVID-19 vaccine." (PMID 38932387, 2024). "The role of TNF-a and IL17a in COVID-19 severity is particularly intriguing." (PMID 39203987, 2024).
COVID-19 (continued). "Moreover, age, BMI, fever duration, leucocyte count, lymphocyte proportion, proportion of CD3+ T cells, tumor necrosis factor α (TNF-α), and IL-10 were confirmed to be independently associated with severe H1N1 infection in post-COVID-19 era." (PMID 38566022, 2024). "The authors hypothesised that this could be partly explained by inhibition of the JAKs pathway, TNF, IL-1 and granulocyte-macrophage colony-stimulating factor, all of which are involved in the COVID-19-related cytokine storm syndrome." (PMID 38807049, 2024). "The analysis conducted allowed us to identify specific structural features within molecules of the furosemide family that directly interact with key active sites involved in the progression of COVID-19, particularly regarding anti-inflammatory cytokine activity against IL-6 and TNF-α." (PMID 39065617, 2024). "Glutamine supplementation (10 g/3x daily) for 5 days could reduce serum levels of IL-1β, hs-CRP, TNFα and increase appetite in COVID-19 patients with pulmonary complications." (PMID 38555403, 2024). "In addition to inhibition of the TNFα, IL-1β and IL-6 induced NF-κB activation, several COVID-19 drugs inhibit the NF-κB activation through disrupting the crosstalk signaling, such as MAPK(JNK/ERK/p38), ANG II-AT1R and ACE2-MAS signaling pathways." (PMID 37872376, 2024). "Although previous studies have linked IP-10 to the development of severe COVID-19, its role in early warning of disease development has not been fully explored, in contrast to cytokines such as IL-6 and TNF-α, which have been widely studied." (PMID 38710800, 2024). "TNF-α levels were significantly higher in patients with postacute COVID-19 than in those with no prior exposure to COVID-19, according to a German cohort study that recruited post-COVID-19 patients." (PMID 38550672, 2024). "The pro-inflammatory cytokines that signal via the JAK-STAT signalling pathway include IL-2, IL-6, IL-8 and TNF-α, all of which are elevated in severe COVID-19, as well as antiviral or anti-inflammatory cytokines such as IFN-γ and IL10, which are also elevated in severe COVID-19." (PMID 39051370, 2024). "Severe COVID-19 is associated with a cytokine storm characterized by elevated plasma concentrations of interleukins (IL-1ß, IL-2, IL-6, IL-7, IL-8, IL-10 and IL-17), interferons, monocyte chemoattractant protein 1 (MCP-1) and TNF-alpha." (PMID 38732160, 2024). "Additionally, the inflammatory cytokine storm induced by COVID-19, characterized by elevated levels of cytokines such as IL-6 and TNF-α, can create a tumor-friendly microenvironment." (PMID 39156288, 2024). "Hence, T-cell counts in COVID-19 were subsequently shown to be negatively correlated with IL-6, TNF-α and IL-10 blood levels, particularly in the elderly." (PMID 39896810, 2024). "However, the expression of tumor necrosis factor (TNF) messenger RNA (mRNA) remained unchanged in patients with COVID-19 compared to controls." (PMID 39519351, 2024). "A significant statistical difference was found between COVID-19 patients and the control group regarding the frequency of TNF-rs1800629 G>A genotypes (P = 0.025), where the GA genotype was significantly higher in the patient group (30.43%) than the control group (17.39%)." (PMID 38544825, 2024). "In our investigation, we discerned that the levels of S1RBD IgG, along with cytokines IL-6, IL-6R, TNF-α, IL-10, and IL-1β, were markedly elevated in the individuals who received two or three doses of the mRNA COVID-19 vaccine compared to those who received a single dose." (PMID 38932387, 2024). "In the present study, the enrichment of these common DEGs in inflammatory response processes and signaling pathways, such as TNF-α, NF-κB, and MAPK, highlights the long-term transcriptional changes associated with the persistent inflammatory state and complications in severe COVID-19 patients." (PMID 39205185, 2024).